MTDH (metadherin)
Diseases named in the same sentence as MTDH in open-access papers (continued):
Sharing a sentence is not in itself a finding about the gene and the disease.
colon carcinoma (11 papers, 2012 to 2025). "In the present study, we therefore examined the frequency and spectrum of MTDH variants, and their relationship to clinicopathological variables in 356 CRC patients including tumor tissue as well as in three colon cancer cell lines." (PMID 26983693, 2016). "Furthermore, OS time in colon cancer patients with positive AEG-1/MTDH and SND1 expression is significantly shorter than in those without AEG-1/MTDH and SND1 expression." (PMID 25009642, 2014). "In colon cancer tissues, a positive correlation has been identified between AEG-1/MTDH and SND1 expression by immunohistochemical staining; AEG-1/MTDH- and SND1-positive expression has been found to significantly correlate with nodal status, pathological stage and differentiation." (PMID 25009642, 2014). "There was no MTDH variant in the colon cancer cell lines SW480, SW620 and HCT116 (data not shown)." (PMID 26983693, 2016). "In predicting the prognosis of colon cancer, the coexpression of AEG-1/MTDH/SND1 may be a novel distinctive marker." (PMID 25009642, 2014).
breast tumor (8 papers, 2014 to 2024). "The third “homing” peptide was a receptor-binding domain of metadherin (MTDH), a cell surface protein in breast tumors shown to home to lung endothelial cells." (PMID 33915737, 2021). "NP-based co-delivery approach can effectively knock down the MTDH gene both in vitro and in vivo, which dramatically inhibits breast tumor growth, achieving effective TAX chemotherapy treatment without overt side effects." (PMID 30227879, 2018). "The analyses of breast tumor samples collected in the USA and Japan revealed strikingly similar patterns of AEG-1/MTDH expression and clinical association." (PMID 25009642, 2014). "Our preceding experiment suggested that MTDH and QPCT were intensively expressed in local advanced breast tumors and positively correlated with poor disease-free survival." (PMID 35875123, 2022). "To confirm the inhibition effect of NP-TAX–siRNA on cell growth, we also tested cell proliferation after NP-TAX–siRNA treatment by using another human breast tumor cell line MDA-MB-435S, which has been demonstrated to express MTDH." (PMID 30227879, 2018). "Surprisingly, MTDH is required for the expansion and function of both luminal and basal breast TICs in diverse breast tumor subtypes, but is non-essential for mammary stem cells, suggesting that it is different from many cell fate determinants that regulate both normal and cancerous stem cells." (PMID 26595523, 2016).
head and neck squamous cell carcinoma (8 papers, 2012 to 2025). A squamous cell carcinoma that arises from any of the following anatomic sites: lip and oral cavity, nasal cavity, paranasal sinuses, pharynx, larynx, and salivary glands. "Increased MTDH is also associated with AKT/PI3K mediated mechanisms of metastasis in head and neck squamous cell carcinoma (HNSCC) patients." (PMID 31131259, 2019). "miR-375 expression suppressed the oncogene AEG-1/MTDH in head and neck squamous cell carcinoma, and knockdown of miR-375 increased the phosphorylation of Akt in BMPACs and post MI heart by targeting PDK-1." (PMID 28186962, 2017). "Recently, metadherin (MTDH, also known as AEG-1 or Lyric), located on human chromosome 8q22, has been identified as an oncogene that can be regulated by HIF-1 signaling pathways in head and neck squamous cell carcinoma (HNSCC)." (PMID 33003428, 2020).
steatosis (8 papers, 2014 to 2025). Increased lipid within the cytoplasm of cells. "Astrocyte elevated gene-1/Metadherin (AEG-1/MTDH)augments lipid accumulation (steatosis), inflammation, and tumorigenesis,thereby promoting the whole spectrum of this disease process." (PMID 36548985, 2023). "Using transgenic mice with hepatocyte-specific AEG-1/MTDH expression, a previous study identified novel aspects of AEG-1/MTDH functions, including the induction of steatosis, the inhibition of senescence and the activation of the coagulation pathway to augment aggressive hepatocarcinogenesis." (PMID 25009642, 2014).
endometrial cancer (7 papers, 2011 to 2021). Primary or metastatic malignant neoplasm involving the endometrium (mucous membrane that lines the endometrial cavity). "This indicates potential baseline resistance to TRAIL in endometrial cancer which could be linked to high MTDH expression." (PMID 21687633, 2011). "An analysis of publicly available datasets showed that the knockdown of MTDH in breast and endometrial cancer cell lines induced the expression RKIP." (PMID 33802672, 2021). "As expected, the relative expression of MTDH in three breast and two endometrial cancer cell lines was lower in the knockdown condition compared to normal control." (PMID 33802672, 2021). "This is also supported by our previous studies using IHC on human endometrial cancer samples, which showed that MTDH expression increases with increasing stages of endometrial cancer." (PMID 31527591, 2019). "MTDH was highly expressed at the protein level in all six endometrial cancer cell lines tested (RL95, AN3CA, KLE, Ishikawa, Hec50co and ECC1)." (PMID 21687633, 2011). "In this study, we investigated the role of MTDH in endometrial cancer and its inhibition as a mechanism to overcome drug resistance." (PMID 21687633, 2011). "In this present study, we focused on the therapeutic benefit of MTDH depletion in endometrial cancer cells to restore sensitivity to cell death." (PMID 21687633, 2011). "Here we report that expression of MTDH is highly elevated in endometrial cancers tissues compared to normal endometrium." (PMID 21687633, 2011). "A similar phenotype was also observed upon knockdown of MTDH in Ishikawa H Type I endometrial cancer cells, indicating that elevated MTDH expression is generally required for endometrial cancer colony formation." (PMID 21687633, 2011). "Our data indicate that depletion of MTDH in endometrial cancer cells resulted in sensitization of cells that were previously resistant in response to combinatorial treatment with TRAIL and the HDAC inhibitor LBH589." (PMID 21687633, 2011). "We also examined the changes in gene expression in Ishikawa H endometrial cancer cells in response to MTDH silencing and observed some overlap with genes that were altered in Hec50co cells." (PMID 21687633, 2011). "MTDH is also highly expressed in advanced endometrial cancers, a disease for which new therapies are urgently needed." (PMID 21687633, 2011). "Specifically, the expression of 80 kDa MTDH and putative 50–55 kDa MTDH isoforms were significantly higher in endometrial cancer samples including papillary serous, sarcoma, and adenocarcinoma, whereas MTDH was undetectable in normal endometrial tissues." (PMID 21687633, 2011). "In endometrial cancer patient tissues, MTDH expression was elevated compared to normal endometrium." (PMID 21687633, 2011). "This is the first report of MTDH's impact on resistance in targeted therapy for endometrial cancer." (PMID 21687633, 2011). "Due to the elevated expression of MTDH in the various endometrial cancer cell lines and human endometrial cancer samples, we next examined the tumorigenic potential of MTDH in the Type II endometrial cancer cell line Hec50co using a short-hairpin RNA (shRNA) specific for MTDH." (PMID 21687633, 2011). "Our identification of the over-expression of MTDH leading to increased PIP3 levels provides yet another potential explanation for the high activity of PI3K and AKT frequently found in endometrial cancers." (PMID 21687633, 2011). "Calb1 and galectin-1 are two putative MTDH downstream genes that may regulate the metabolism of phosphatidylinositol, which is part of the PI3K/AKT signaling pathway commonly upregulated in endometrial cancer." (PMID 21687633, 2011).
lung squamous cell carcinoma (7 papers, 2015 to 2024). "For example, the miR-145-5p and -3p coordinately target MTDH, whose high expression reduces lung squamous cell carcinoma patients." (PMID 34230481, 2021). "For example, miR-145-3p and -5p inhibit the aggressiveness of bladder cancer cells by suppressing UHRF1 and function as tumor suppressor in lung squamous cell carcinoma through down-regulation of MTDH." (PMID 31262974, 2019).
pancreatic cancer (7 papers, 2014 to 2024). "To clarify this hypothesis both in vitro and in vivo, we attempted MTDH knockdown using two short hairpins targeting MTDH (MTDH shRNA-1 and MTDH shRNA-2) in KPCY cells, lineage YFP-labeled cancer cells from pancreatic tumor-bearing KPCY mice." (PMID 29029495, 2017).
bladder cancer (6 papers, 2016 to 2022). "For example, miR-145-3p and -5p cooperatively regulate cancer progression and aggressiveness of lung and bladder cancer by suppressing metadherin (MTDH) and ubiquitin-like with PHD and ring finger domains 1 (UHRF1), respectively." (PMID 31262974, 2019).
rectal cancer (6 papers, 2012 to 2026). A primary or metastatic malignant neoplasm that affects the rectum. "Experimental validation confirmed significantly elevated MTDH expression in both radioresistant rectal cancer specimens and corresponding cellular models." (PMID 42065055, 2026). "MTDH level was also examined in tissues from 82 rectal cancer patients who were responsive or non-responsive to radiotherapy." (PMID 42065055, 2026).
head and neck cancer (5 papers, 2018 to 2022). A primary or metastatic malignant neoplasm affecting the head and neck. "Numerous studies and our previous work showed that high expression of MTDH promoted EMT in head and neck cancers." (PMID 34622157, 2021). "Our previous work and other colleagues’ studies showed that MTDH is an oncogene and a trigger that activates PI3K, MAPK, and WNT pathway in head and neck cancer and other types of cancer, which indicates MTDH would serve as an unfavorable prognosis indicator for patients with cancer." (PMID 34622157, 2021).
invasive breast carcinoma (5 papers, 2010 to 2022). A carcinoma that infiltrates the breast parenchyma. "Further survival analysis showed that high MTDH expression was an adverse prognostic factor for invasive breast cancer (P = 0.039)." (PMID 27229534, 2016). "Down-regulation of MTDH reduces cell proliferation and increases apoptosis, while MTDH overexpression indicates poor prognosis in invasive breast cancer." (PMID 25417825, 2014). "In summary, AEG-1/MTDH overexpression contributes to an aggressive phenotype, leading to a poor prognosis in primary invasive breast cancer." (PMID 25009642, 2014). "Furthermore, 90/162(55.56%) cases of invasive breast cancer showed MTDH overexpression." (PMID 20565850, 2010).
metastatic cancers (5 papers, 2015 to 2021). A carcinoma which has spread from the original site of growth to another anatomic site. "Several previous studies suggest that MTDH could contribute to cancer progression, and it is considered a hallmark protein of metastatic cancers." (PMID 33802672, 2021).
squamous cell carcinoma (5 papers, 2011 to 2021). A carcinoma arising from squamous epithelial cells. "The activation of NF-κB by CCL18 also increases the expression of metadherin (MTDH), which leads to the EMT of the cells of the squamous cell carcinoma of the head and neck." (PMID 33114763, 2020).
thyroid cancer (5 papers, 2020 to 2024). "This study confirmed that MTDH expression is significantly increased in various tumors than paired adjuvant normal tissues except for thyroid cancer." (PMID 34622157, 2021). "The downregulated expression of MTDH in thyroid cancer was in contrast to the previous thyroid cancer publication." (PMID 34622157, 2021).
benign prostatic hyperplasia (4 papers, 2014 to 2021). A non-cancerous nodular enlargement of the prostate gland. "However, there is evidence demonstrating that MTDH is expressed at higher levels in PC samples, compared with those of benign prostatic hyperplasia." (PMID 25684730, 2015). "A significantly higher expression of AEG-1/MTDH has been identified in PC samples and cell lines compared with benign prostatic hyperplasia tissue samples and normal prostate epithelial cells." (PMID 25009642, 2014).
prostate adenocarcinoma (4 papers, 2014 to 2024). "The Cancer Genome Atlas (TCGA) prostate adenocarcinoma (PRAD) cohort was used to compare CD44v5 exon expression between patients with either high or low metadherin expression (separated by median expression)." (PMID 31450747, 2019).
tongue squamous cell carcinoma (4 papers, 2016 to 2023). A squamous cell carcinoma that arises from the tongue. "MTDH promoted EMT of tongue squamous cell carcinoma (TSCC) through activating Wnt/PCP signaling pathway." (PMID 28107197, 2017).
cholangiocarcinoma (3 papers, 2022 to 2025). A carcinoma that arises from the intrahepatic biliary tree (intrahepatic cholangiocarcinoma) or from the junction, or adjacent to the junction, of the right and left hepatic ducts (hilar cholangiocarcinoma). "The AEG-1/MTDH gene is amplified in HCC but not in cholangiocarcinoma." (PMID 40282551, 2025). "Interestingly, while AEG-1/MTDH gene amplification was observed in HCC patients, no such gain was detected in cholangiocarcinoma patients, thereby stressing the importance of AEG-1 in HCC regulation." (PMID 40282551, 2025).
diffuse large B-cell lymphoma (3 papers, 2012 to 2014). "A recent study has suggested that AEG-1/MTDH contributes to the pathogenesis of diffuse large B-cell lymphoma mediated through regulation of the Wnt/β-catenin pathway." (PMID 25009642, 2014). "However, the expression and role of MTDH in diffuse large-B-cell lymphoma (DLBCL) have not been reported yet." (PMID 22768080, 2012).
HIV-1 infection (3 papers, 2011 to 2017). The type species of lentivirus and the etiologic agent of acquired immunodeficiency syndrome (AIDS). "Metadherin (MTDH) is reported as a neuropathology-associated gene produced in human fetal astrocytes following HIV-1 infection or treatment with recombinant HIV-1 envelope glycoprotein." (PMID 27229534, 2016). "Metadherin (MTDH, also known as AEG-1, and Lyric), was first reported in 2002 as a novel late response gene following HIV-1 infection or treatment with recombinant HIV-1 envelope glycoprotein (gp120)." (PMID 21408129, 2011).
ovarian tumor (3 papers, 2014 to 2025). "We found that MTDH was highly abundant in KURAMOCHI compared to other cell lines, and complementary analysis using the cProSite resource indicated that MTDH expression is significantly elevated in ovarian tumor tissue relative to adjacent normal tissue." (PMID 41286067, 2025). "Borderline ovarian tumours demonstrated statistically significant higher expression of AEG-1/MTDH compared to the benign cystadenomas (Mann Whitney U-test, P < 0.001)." (PMID 24963474, 2014). "Furthermore, proteomic data from cProSite, showed significantly higher MTDH expression in ovarian tumors compared to adjacent normal tissues (p-value < 0.008)." (PMID 41286067, 2025). "Similarly to MTDH, analysis of cProSite data indicated significantly higher levels of SND1 expression in ovarian tumor tissues relative to adjacent normal tissues (p-value < 0.0001)." (PMID 41286067, 2025).
benign cystadenomas (2 papers, 2014 to 2021). "There was no AEG-1/MTDH expression noted in normal ovarian tissue, 30/31 benign cystadenomas and 1 borderline ovarian tumour." (PMID 24963474, 2014).
clear cell renal cell carcinoma (2 papers, 2020 to 2024). "MTDH promoted the metastasis of clear cell renal cell carcinoma by activating SND1-mediated ERK signaling and epithelial-mesenchymal transition." (PMID 31978894, 2020). "MTDH promoted metastasis of clear cell renal cell carcinoma by activating the SND1-mediated ERK and EMT signaling pathways." (PMID 31978894, 2020).
Cluster headache (2 papers, 2018 to 2025). A type of headache characterized by repeated attacks of unilateral pain lasting 15 to 180 minutes and associated with local autonomic signs. "We found a trend for association between rs1835740, which is reported to affect MTDH mRNA levels, and cluster headache in our Swedish case-control material (p = 0.043, Χ2 = 4.102)." (PMID 30382894, 2018).
laryngeal carcinoma (2 papers, 2017 to 2023). Carcinoma that arises from the laryngeal epithelium. "In laryngeal cancer, miR-217 exerts an anti-metastatic and antiproliferative effect via repression of its downstream target genes MTDH and the programmed cell death protein 1-ligand 1 (PD1-L1) at the translational level." (PMID 37711209, 2023).
leukaemia (2 papers, 2018 to 2020). "However, there are limited reports on the role of MTDH in leukaemia." (PMID 32251289, 2020).
mucosal melanoma (2 papers, 2019 to 2021). A melanoma that arises from a mucosal site. "In conclusion, our results suggested that miR-let-7b and miR-let-7c inhibited the recurrence of mucosal melanoma through inhibiting cell growth, migration and invasion, inducing cell apoptosis and cell cycle arrest by targeting MTDH and CALU." (PMID 31118065, 2019). "Our results suggested that miR-let-7b and miR-let-7c inhibited the recurrence of mucosal melanoma through inhibiting cell growth, migration, invasion and metastasis, inducing cell apoptosis and cell cycle arrest by targeting MTDH and CALU." (PMID 31118065, 2019).
multiple myeloma (2 papers, 2016 to 2021). "To query the mechanism underlying the Bortezomib treatment induced MTDH reduction, we explored MTDH neighbor genes using Myeloma Portal, and MMSET/WHSC1 was identified as the most relevant gene with MTDH." (PMID 26683226, 2016). "However, the function of MTDH in multiple myeloma (MM) is still unexplored." (PMID 26683226, 2016). "To trace the role of MTDH in MM, we examined MTDH expression in normal plasma (NP), monoclonal gammopathy of undetermined significance (MGUS, a pre-MM disease) and myeloma cells using our gene expression profiling (GEP) database." (PMID 26683226, 2016). "However the function of MTDH in multiple myeloma (MM) is still not elucidated and requires further exploration." (PMID 26683226, 2016).
prostate tumor (2 papers, 2014 to 2015). "AEG-1/MTDH also modulates the BCCIPα protein levels in prostate tumor cells through an indirect mechanism involving the NF-κB signaling pathway." (PMID 25009642, 2014).
acute myeloid leukemia (1 paper, 2014). Acute myeloid leukemia (AML) is a group of neoplasms arising from precursor cells committed to the myeloid cell-line differentiation. "Furthermore, in the carcinogenesis of acute myeloid leukemia (AML), a novel functional link has been revealed between AEG-1/MTDH and Aurora A kinase (AURKA) with regard to Akt1 activation." (PMID 25009642, 2014).
Alzheimer disease (1 paper, 2025). A progressive, neurodegenerative disease characterized by loss of function and death of nerve cells in several areas of the brain leading to loss of cognitive function such as memory and language. "Astrocyte elevated gene-1 (AEG-1), also known as Metadherin (MTDH) or Lysine-Rich CEACAM1 co-isolated (LYRIC), is firstly identified in the astrocytes of HIV-infected patients with Alzheimer’s disease." (PMID 40122859, 2025).
benign ovarian tumours (1 paper, 2014). "Furthermore, high AEG-1/MTDH expression could distinguish borderline from benign ovarian tumours with an associated probability of 95.6%, whereas high p50 and p65 expression was associated with a probability of 89.1% and 91.3%, respectively." (PMID 24963474, 2014).
Crohn disease (1 paper, 2025). A gastrointestinal disorder characterized by chronic inflammation involving all layers of the intestinal wall, noncaseating granulomas affecting the intestinal wall and regional lymph nodes, and transmural fibrosis. "By integrating multi-omics approaches, this study reveals a crucial connection between ferroptosis and immune microenvironment dysregulation in Crohn’s disease (CD), identifying seven hub ferroptosis-related differentially expressed genes (FEDGs): SCD, ATF4, SAT1, RPL8, MUC1, MTDH, and ATP6V1G2." (PMID 41515900, 2025).
ductal carcinoma (1 paper, 2010). "This may suggest that MTDH plays a more important role in initiation of ductal carcinoma." (PMID 20565850, 2010).